CRP (C-reactive protein)
Diseases named in the same sentence as CRP in open-access papers (continued):
Sharing a sentence is not in itself a finding about the gene and the disease.
Hypertension (continued). "Besides, habitual breakfast skipping is associated with higher levels of systematic inflammatory markers such as C-reactive protein and glycoprotein acetyl, which may suggest chronic inflammation as a possible molecular basis for the association between skipping breakfast and hypertension." (PMID 35284139, 2022). "Hypertension may promote inflammation of the blood vessels by increasing mechanical stress on arterial walls and normal CRP levels could be prevented against hypertension in animal models and humans." (PMID 36262245, 2022). "Associations between hypertension with TNF-α, IL-6, and CRP have been reported, suggesting that inflammation may link cataract and hypertension." (PMID 35565652, 2022). "The variables predicting severe disease in PsA at the following visit and selected in this analysis were patient global pain, clinical form at diagnosis, psoriasis affecting the gluteal cleft and/or perianal area, treatment with synthetic DMARDs, arterial hypertension, and high CRP." (PMID 35572968, 2022). "Furthermore, we included elderly patients, and because co-morbidity is common in elderly patients, it was not possible to set up a healthy population as a control group to assess the relationship between CRP and hypertension." (PMID 36418968, 2022). "However, fewer experiments have been conducted nationally and internationally to study the correlation between CRP levels and hypertension in older adults over 65 years of age, especially in the elderly." (PMID 36418968, 2022). "Body mass index ≥ 25 and <30 kg/m2, body mass index ≥ 30 kg/m2, snoring, obstructive apnoea syndrome sleep, hypertension, type 2 diabetes, CRP levels ≥ 1 and <3 mg/L, CRP levels ≥ 3 mg/L, and alexithymia were associated with an increased risk of dyslipidaemia in major depressed individuals." (PMID 35755481, 2022). "Therefore, the main purpose of our study was to explore the relationship between CRP and hypertension in the elderly, and to provide support for the prevention of early hypertension and common diseases in the elderly." (PMID 36418968, 2022). "The results of Kaplan–Meier analysis also showed that age more than 60, WBC more than 6.5 × 109, CRP more than 15 mg/L, PLT more than 250 × 109, and hypertension were independent risk factors which could increase the probability of HF." (PMID 35559036, 2022). "Therefore, hypertension is a powerful trigger for vascular inflammation, and CRP provides a synergistic effect, leading to an increase in the risk of stroke among individuals." (PMID 36262245, 2022). "In the present study, CRP was associated with higher UA, while hypertension and blood pressure were not." (PMID 35885024, 2022). "Notably, the predictive value of some inflammation biomarkers like C-reactive protein (CRP) for the incidence of hypertension or the clinical outcomes has been explored in several studies." (PMID 36195874, 2022). "The comparison of Hcy and CRP levels among three clusters remained significant after adjustment for age of diagnosis, sex and significant comorbidities including hypertension, hyperlipidemia, lipid medication and hypertension medication." (PMID 36038597, 2022). "The generated risk assessment models included age, reduced left ventricular ejection fraction, reduced right ventricular function, moderate/severe tricuspid regurgitation, systolic pulmonary artery pressure, arterial hypertension, d‐dimer, CRP, PCT, TnI, LDH, GPT, and/or NT pro‐BNP." (PMID 35789499, 2022). "After adjustments for age, sex, screening center, triglycerides, BMI, history of hypertension, CRP, HOMA-IR, smoking status, and alcohol intake, the adjusted mean of log (CAC score + 1) in osteosarcopenia group was higher than other three groups (all p value < 0.0001, Bonferroni post-hoc analysis)." (PMID 35379833, 2022).
Hypertension (continued). "The elevated-CRP levels may promote thrombotic events by inducing monocytes to express tissue factors for IS, additionally, the small arteries seem prone to hypertension-induced vascular injury." (PMID 36262245, 2022). "Therefore, we believe that the co-occurrence of CRP levels elevation and hypertension can accelerate the progression of atherosclerosis and cerebral vascular injury than the separation of both performed." (PMID 36262245, 2022). "Log CRP was associated with increased risk of prevalent hypertension (PR = 1.03; 95% CI 1.02,1.04) but did not change the association of HBA copy number with prevalent hypertension." (PMID 35834496, 2022). "Differences in age, sex, TG, TC, ALT, TBil, hs‐CRP, the prevalence of hypertension, physical exercise, current smoker, family income, liver cirrhosis, fatty liver, gallstone disease and gallbladder polyp were found between HBsAg seropositive group and HBsAg seronegative group (P < .05)." (PMID 34855203, 2022). "There was also trend to associations for hs-CRP, baseline SBP and prior hypertension crisis." (PMID 35455652, 2022). "Srećković B and colleagues showed that patients with MS had statistically significant higher values ​​of abdominal obesity, hypertriglyceridemia, hypertension, IR, CRP, microalbuminuria and homocysteine, which promote endothelial dysfunction and accelerated development of vascular complications." (PMID 36685849, 2022). "Covariates were included if there were statistically significant differences in frequencies or medians and/or standardized differences of >0.25 between the two groups (arterial hypertension, treatment with beta blockers, treatment with colchicine, age, CRP, leukocyte count)." (PMID 35200686, 2022). "Furthermore, individuals with high CRP and simultaneous hypertension were older, smokers, living in urban localities, had lower income, poorer basic ADL scores and instrumental ADL scores, poor marital status, and a higher BMI." (PMID 36262245, 2022). "According to some authors, the risk factors for the development of pulmonary fibrosis include older age, severe dyspnea, tachypnea, hypertension, intensive care unit stays, acute respiratory distress syndrome, invasive ventilation therapy, lymphocytopenia and high CRP levels." (PMID 35330108, 2022). "In addition, other risk factors in adults hospitalized with COVID include hypertension, baseline CKD ≥ stage 3, low hemoglobin, low CRP, nephrotoxin exposure, and congestive heart failure have been associated with AKD." (PMID 36340722, 2022). "Interestingly, higher CRP levels were also reported in patients with arterial hypertension and endothelial dysfunction." (PMID 35887545, 2022). "Predictive models included age (for both outcomes), hypertension, Framingham risk score and C-reactive protein (for PWV), but not sclerostin." (PMID 36517533, 2022). "A high percentage of the respondents have high cholesterol, high blood pressure, and CRP." (PMID 35628058, 2022). "It was suggested that ESR is more influenced by sex (elevated in females) and age, while the CRP levels may be affected by smoking, high blood pressure, and high BMI." (PMID 36264948, 2022). "CRP may predict the burden of atherosclerosis, since it is a systemic marker of inflammation, and is also aggravated by high blood pressure." (PMID 36262245, 2022). "These include high blood pressure, aberrant serum lipids (high cholesterol, triglycerides, and atherogenic lipoproteins) and elevated serum glucose and pro-inflammatory serum markers, such as adipokines (e.g., leptin) and C-reactive protein (CRP)." (PMID 35268057, 2022). "In the NHANES study, higher HBI was associated with more favorable lipid profiles, lower hypertension risk in men, and lower CRP, but not with MetS." (PMID 35071290, 2021). "It is worth noting that Asians tend to have lower CRP concentrations and lower BMI, which may be confounding factors for CRP predicting the occurrence of hypertension." (PMID 34925916, 2021).
Hypertension (continued). "Several epidemiological studies have explored the association between CRP levels and the risk of hypertension, but there is no consistent conclusion regarding the predictive ability of CRP." (PMID 34925916, 2021). "By univariate analysis, age, hypertension, neutrophils, lymphocytes and platelets counts, alanine aminotransferase, aspartate aminotransferase, albumin, urea, calcium, phosphorus, bicarbonate, APTT, PT, d-dime, CRP, PCT, and LDH, were associated with AKI." (PMID 34541999, 2021). "The complex relationship between CRP and hypertension may be better understood by investigating the contribution of these confounding factors to the pathogenesis of hypertension." (PMID 34925916, 2021). "The proportion of the effect of BMI on severity of COVID‐19 mediated by CRP, glycemia or hypertension, we find that glucose mediated 79% (p < .0001), LDH mediated 78% (p < .0001), hypertension mediated 66% (p < .0001); however, only 44% (p < .005) was mediated by systemic inflammation (CRP)." (PMID 33851033, 2021). "CRP levels have been frequently shown, independent of multiple risk factors, to predict the onset of hypertension as well as future increases in SBP but not DBP among normotensive individuals." (PMID 34943129, 2021). "A prospective study that followed middle-aged Japanese men without hypertension for 9 years demonstrated that sustained elevations in serum C-reactive protein (CRP) were associated with a longitudinal increase in baPWV." (PMID 34820427, 2021). "Second, there is a positive correlation between CRP levels and future incidence of hypertension; as such, targeting inflammatory pathways may be a potential avenue for the prevention or treatment of hypertension." (PMID 34925916, 2021). "In the univariate analysis, the male sex, underlying malignancy, DM, hypertension, elevated serum ALT levels, decreased serum albumin levels, increased hs-CRP and PCT levels, maximal diameter of abscess, PCD insertion, and culture positivity were associated with prolonged hospitalization." (PMID 33573593, 2021). "The inflammation marker CRP was a risk factor associated with short‐term mortality in patients with hypertension, but not liver diseases." (PMID 33112011, 2021). "CRP was an independent risk factor associated with short‐term mortality in patients with hypertension, but not liver diseases." (PMID 33112011, 2021). "Furthermore, we identified risk factors for AKD development, namely prior diagnosis of hypertension and CKD, lower hemoglobin and lower CRP at the hospital admission and nephrotoxin exposure during admission." (PMID 34640618, 2021). "Thirdly, due to the availability of data, we only used the 2009 biomarker data, but the intrinsic associations between CRP and hypertension are not affected by economic and social development." (PMID 34925916, 2021). "A possible mechanism by which high CRP levels lead to hypertension may be that increased CRP levels may increase blood pressure by decreasing nitric oxide production in endothelial cells, leading to vasoconstriction." (PMID 34925916, 2021). "Meanwhile, CRP has also been reported to have proatherogenic properties by upregulating the expression of angiotensin type I receptors, thereby affecting the renin-angiotensin system and participating in the pathogenesis of hypertension." (PMID 34925916, 2021). "It has also been shown that CRP mediates the relationship between BMI and hypertension." (PMID 34925916, 2021). "Moreover, all included patients had high blood pressure and the prevalence of overt cases of hypertension were marked in T2D with high CRP levels." (PMID 35844722, 2021). "Moreover, higher levels of CRP were found in patients with hypertension [OR (95%CI) = 1.22 (1.04–1.41), p = 0.012], DM [OR (95%CI) = 1.34 (1.17–1.52, p < 0.001] and dyslipidaemia [OR (95%CI) = 1.4 (1.08–1.82), p = 0.012]." (PMID 34062730, 2021).
Hypertension (continued). "Elevated c-reactive protein, atrial fibrillation, hypertension and steroid use may be used as predictors of SCAD mortality." (PMID 33903608, 2021). "Higher peripheral neutrophil count group population were more likely to be male and smoker, had DM and hypertension as a co-morbidity, had higher BMI and serum levels of uric acid, hs-CRP, calcium, hemoglobin, and proteinuria, and had lower levels of eGFR and phosphate." (PMID 34710093, 2021). "The age, baseline SpO2, the ordinal scale of 4 and 5, neutrophil and platelet count, estimated glomerular filtration rate, and C-reactive protein concentration as well as malignancy and arterial hypertension were the independent predictors of 28-day mortality in logistic regression analysis." (PMID 34068725, 2021). "However, history of hypertension and CAD, the elevated hs-CRP and D-dimer levels were independent risk factors only in the men." (PMID 33664674, 2021). "Metformin (100-500 mg/kg/d) treatment increases NO bioavailability and attenuates high-sensitivity CRP (hCRP)-induced hypertension by activating of AMPK/peroxisome proliferator-activated receptor δ (PPARδ) pathway 190 and AMPK-eNOS phosphorylation pathway 191 in animal studies." (PMID 34646376, 2021). "Because part of T1DM patients received Ramipril due to arterial hypertension, this treatment might have also contributed to low CRP response to exercise in this group." (PMID 33633280, 2021). "CRP was a risk factor associated with short‐term mortality in patients with hypertension, but not liver diseases; additionally, D‐dimer was a risk factor for death in patients with liver diseases." (PMID 33112011, 2021). "This fact could explain the loss of significance of the NPR in the most robust multivariate analysis and the association with mortality of age over 70 years with sex, hypertension, Sa O2 > 90, LDH > 677 U/L and CRP > 131 mg/L." (PMID 34315437, 2021). "In addition in model 5, WC and BMI interfered with the relationship of CRP to the incidence of hypertension." (PMID 34925916, 2021). "In addition, the risk of severity was closely related to fatigue, chest tightness, hypertension, and C-reactive protein." (PMID 34495869, 2021). "The univariate analysis indicated that the higher neutrophil group was significantly associated with male gender, higher BMI and smoker, co-morbidity of DM, hypertension, lower eGFR and phosphate levels, and higher uric acid, hs-CRP, calcium, hemoglobin, and proteinuria levels." (PMID 34710093, 2021). "Male, aged, hypertension comorbidity, abnormal routine blood results, raised creatine kinase, glutamic oxaloacetic transaminase, lactate dehydrogenase, CRP, procalcitonin, D-dimer, FbG, APTT, and positive in proteinuria can be candidates for early warning indicators of severe disease." (PMID 34002684, 2021). "TAK patients with and without intracranial vascular disease were compared with respect to age at diagnosis, frequencies of smoking (current or former), hypertension, the presence of carotid artery involvement, c-reactive protein (as a surrogate for disease activity), and Numano classification." (PMID 34829344, 2021). "Likewise, studies report a correlation between cytokines such as IL-6, TNFα, and C-reactive protein and blood pressure in patients with essential hypertension." (PMID 33953971, 2021). "Because MR analyses showed that high blood pressure and smoking were the only two factors causally and independently associated with IA, we assessed the genetic correlation of sIL6R and CRP with IA both before and after conditioning IA on high blood pressure and/or smoking." (PMID 34168680, 2021). "To fully understand the factors influencing the development of PAD, we tried to include more parameters, and found the independent risk factors for PAD in elderly patients with T2DM were age, smoking habit, hypertension, diabetic neuropathy, hs-CRP and hyperuricemia." (PMID 32968406, 2020).
Hypertension (continued). "The patients with severe WMLs were significantly older, were more likely to be female, and had lower BMIs, lower rates of current smoking and daily alcohol habit, higher rates of hypertension, chronic kidney disease, and history of stroke, and higher serum CRP levels than patients with mild WMLs." (PMID 33031428, 2020). "There was a positive association between the tertiles of whole blood iron and incidents of hypertension and hyperglycemia, and the odds ratios (ORs) for individuals categorized in tertile three after adjusting for age, gender, CRP, and BMI was 4.07 and 1.74, respectively." (PMID 32443740, 2020). "Many inflammatory markers such as C-reactive protein (CRP), cytokines, and adhesion molecules have been found to be elevated in hypertensive patients supporting the role of inflammation in the pathogenesis of hypertension." (PMID 33224035, 2020). "Patients in PAD group had older age, longer durations of T2DM, a higher prevalence of hypertension, diabetic neuropathy and hyperuricemia, a higher proportion of smoking habit and alcohol use, a higher value of hs-CRP, white cell count and lymphocyte count, compared with those in non-PAD group." (PMID 32968406, 2020). "Memory performance at 1 year was not significantly predicted by weight loss, changes in C-reactive protein levels or postoperative somatic comorbidity (Type 2 diabetes, sleep apnea, and hypertension)." (PMID 33488469, 2020). "Among the remaining outcomes without well-established effects from RCTs, we identified evidence of novel associations between an increased GRS for CFT with adverse effects on creatinine, HDL, apolipoprotein A, hypertension, and spinal stenosis, but beneficial effects on C-reactive protein." (PMID 33063668, 2020). "Recently, elevated plasma inflammatory markers, including hs-CRP and IL-6, have been reported to be nonsignificantly related to a higher risk of hypertension." (PMID 32292598, 2020). "These factors included elevated on-admission disease activity (P < 0.001), lower DLCO% (P = 0.010), serum ferritin (P = 0.058), CRP (P = 0.037), hypertension (P = 0.065), allergic history (P = 0.058), treatment of steroid + IVIG (P = 0.038), and diagnosis of CADM (P = 0.038)." (PMID 32083087, 2020). "Patients who experienced poor outcomes were older, more likely suffered from hypertension, cardiovascular comorbidities, and nicotine abuse, and had a more severe H-H grade, larger aneurysm size, and higher serum levels of glucose and CRP compared with those who presented with good outcomes." (PMID 32075656, 2020). "Significant differences were observed for age, sex, body-mass index, AF type, LAD and LVEF in the baseline echocardiogram, white blood cell count, for the frequency of hypertension and heart failure as well as for the history of amiodarone treatment across CRP categories." (PMID 32993521, 2020). "Hypertension causes increased release of both ICAM-1 and IL-6; that in turn stimulate CRP release." (PMID 33204538, 2020). "Higher CRP serum levels were found in participants who reported one or more chronic disease, in particular hypertension (OR 1.58, 95% CI 1.15;2.17), had a BMI value greater than 30 (OR 2.12, 95%CI 1.60;2.81), and achieved low scores in the physical domain of the SF12 (OR 1.68, 95%CI 1.28;2.21)." (PMID 30728031, 2019). "Compared with the analytical sample, participants who were excluded were older, had higher baseline CRP values and lower education, and were more likely to be current smokers, to have hypertension, to be less physically active, to have depressive symptoms, and to report limitations with ADL." (PMID 29462285, 2019). "As can be observed, age (p<0.001), BMI (p<0.004), waist circumference (p<0.001), hypertension (p<0.005), serum CRP concentrations (p<0.04) and HOMA-IR (p<0.004) were higher in psoriasis patients with femoral and/or carotid plaques than in those with no atherosclerotic plaque." (PMID 30735527, 2019).